BRAF (B-Raf proto-oncogene, serine/threonine kinase)
Diseases named in the same sentence as BRAF in open-access papers (continued):
Sharing a sentence is not in itself a finding about the gene and the disease.
colon carcinoma (continued). "We found that BRAF mutant colon cancer had higher stromal score (p = 0.02), immune score (p < 0.0001), ESTIMATE score (p = 0.0001), and lower tumor purity (p = 0.0003)." (PMID 34381786, 2021). "Altogether, data from in vitro and in silico studies indicate an increased abundance of nucleophosmin in BRAF mutant colon cancer." (PMID 34201061, 2021). "While KRAS has been, until recently, seen to be undruggable and the new KRAS inhibitors target only the less frequent mutation G12C, several BRAF and MEK kinase inhibitors have been developed and tested also in colon cancer patients." (PMID 34885128, 2021). "In this study, we will explore the role of major regulators of sphingolipid metabolism and signaling in the development of resistance to vemurafenib in BRAF mutant colon cancer cells." (PMID 34639107, 2021). "Collectively, our study suggests the possibility of using the combination of ABC294640 and PLX4032 as a novel therapeutic approach to combat vemurafenib resistance in BRAF mutant colon cancer, which warrants additional preclinical validation studies." (PMID 34639107, 2021). "It was also found by other studies that biomarkers for the prognosis of colon cancer, including microsatellite instability-high, CpG island methylator phenotype-high, RAS, phosphoinositide 3-kinase pathway, and BRAF mutations." (PMID 33763372, 2021). "A recent meta-analysis found that colon cancer patients with BRAF mutations had worse overall survival (OS) and PFS following anti-EGFR therapies compared to patients with wild-type BRAF tumors." (PMID 32599843, 2020). "The presence of CIMP has been correlated with BRAF mutations (BRAF V600E) in both microsatellite stable and MSI colon cancers." (PMID 32599894, 2020). "Effects of UAG are abrogated in (d) BRAF-transfected MCF7 cells, and (e) BRAF- and (f) KRAS-mutated colon cancer cells (6–12 replicates/group)." (PMID 32667883, 2020). "Tumor molecular markers, such as CpG island methylator phenotype (CIMP) status; driver gene mutations, such as KRAS and BRAF; and tumor immune microenvironment, have been linked to different recurrence risks among stage III colon cancer patients." (PMID 33071795, 2020). "It will be interesting to further explore these associations among hypoxia, BRAF mutation and MSI status, and macrophage infiltration on colon tumors." (PMID 32231135, 2020). "This issue has been addressed in several preclinical and clinical studies, which indicate that EGFR blockade and BRAF targeting act synergistically to inhibit ERK pathway signaling in BRAFV600E mutant colon cancers." (PMID 32066410, 2020). "The extracts were tested using two cell lines representative of the main genetic profiles of human colon cancer, HCT116 (KRAS mutated) and RKO (BRAF mutated) and IC50 and IC25 values determined." (PMID 32806531, 2020). "Based on the results of the analysis, anti-EGFR antibody therapies are recommended for RAS/BRAF wild-type colon cancer when the primary lesion is on the left side, while BEV is recommended for cases in which the primary lesion is located on the right side." (PMID 31203527, 2020). "The selected 299 mutations cover the National Comprehensive Cancer Network (NCCN) guideline of colon cancer recommended gene list relevant to treatment and prognosis, such as KRAS, NRAS, BRAF V600E mutations." (PMID 33008377, 2020).
colon carcinoma (continued). "In a pooled analysis for stage II–III colon cancer, microsatellite instability, and KRAS and BRAF mutation status were used to construct a prognostic model in combination with TNM stage." (PMID 33335852, 2020). "Right-sided colon cancers are characterized by a high frequency of microsatellite instability (MSI) and BRAF mutation." (PMID 33329946, 2020). "Thirdly, we showed by FRET-FLIM imaging an induction of HER2-HER3 dimers after cetuximab treatment in KRAS and BRAF WT colon cancer cells." (PMID 31851321, 2020). "A colon cancer cell line with RNF43-G659Vfs*41 and BRAF-V600E mutations had low levels of Wnt signaling and was inhibited by activation of Wnt signaling." (PMID 31811196, 2019). "A colon cancer cell line with RNF43-G659Vfs*41 and BRAF-V600E mutations was sensitive to activation of Wnt/β-catenin signaling." (PMID 31811196, 2019). "BRAF mutations are reported in less than 10% of cases and have been related to MSI-positive and proximal colon tumors in several studies." (PMID 31548566, 2019). "In the light of these considerations, we assayed the ability of TM treatment to influence signal transduction through the Raf1/MEK/ERK pathway in colon cancer cells bearing different status of BRAF." (PMID 31083627, 2019). "So far, we identified a molecular sub-cluster of colon cancer cells which was sensitive to chemotherapy, BRAF inhibitors, PI3K-mTOR inhibitors and NOTCH inhibitors treatment." (PMID 31596728, 2019). "In the NMF classification, we find that a molecular sub-cluster of colon cancer cells is specifically sensitive to chemotherapy, BRAF inhibitors, PI3K-mTOR inhibitors and NOTCH inhibitor treatment." (PMID 31596728, 2019). "Further studies will be needed to test the possibility of MSI-H colon cancers with BRAF-V600E being sensitive to Wnt activation." (PMID 31811196, 2019). "The association of BRAF-V600E and low Wnt signaling was only found in MSI-H colon tumors which were rarely mutated in APC27." (PMID 31811196, 2019). "Colon tumors with RNF43-G659Vfs*41 had low Wnt/β-catenin signaling and were frequently mutated in BRAF." (PMID 31811196, 2019). "Only a few studies have evaluated the combined impact of CpG island methylation, BRAF mutation status and MSI status on survival for colon cancer." (PMID 31072372, 2019). "In order to better characterize the effect of copper depletion on colon cancer cells bearing wild type or mutant BRAF, we performed a three-dimensional (3D) culture spheroid proliferation assay." (PMID 31083627, 2019). "The effect of copper chelation on the viability of colon cancer cells bearing the wild type or mutant BRAF gene was determined using a colorimetric (WST-1 based) assay." (PMID 31083627, 2019). "For example in colon cancer, the KRAS mutation was found 22-39% and the BRAF mutation was found 2.8-6.6% While, the KRAS and BRAF mutations in mucinous ovarian cancer were 50-75% and 3.5% respectively." (PMID 31030485, 2019). "In this study, we examined the effects of stable HIF-1α or HIF-2α siRNA knockdown on autophagy and drug resistance displayed by RAS-driven and BRAF-driven human colon carcinoma cell lines and in patient-derived primary colon cancer cells." (PMID 31151160, 2019). "We also observed that TM treatment is effective in reducing clonogenic growth of colon cancer HT-29 BRAFV600E cells resistant to BRAF pharmacological inhibition." (PMID 31083627, 2019). "Intriguingly, we found that a colon cancer cell line with RNF43-G659Vfs*41 and BRAF-V600E mutations was sensitive to activation of Wnt signaling in vitro." (PMID 31811196, 2019).
colon carcinoma (continued). "Our data showed that when divided into three or four sub-clusters by NMF classification, each cluster of colon cancer cells demonstrated distinctive response to BRAF inhibitors or PI3K-mTOR inhibitors treatment." (PMID 31596728, 2019). "Both in the MSI and MSS colon carcinoma groups, there is a strong tendency for the co-occurrence of RNF43 with BRAF mutations." (PMID 29652830, 2018). "Several recent clinical trials, carried out on large sets of colon carcinoma patients, have assessed the impact of MMR status and BRAF/KRAS mutations on outcome." (PMID 29652830, 2018). "BRAF-mutant MSS colon carcinomas are particularly important because they have a dismal prognosis and an aggressive clinical course with adverse histologic features, such as lymphatic and perineural invasion and high tumor budding." (PMID 30458818, 2018). "Compared with colon cancer rectal cancer, KRAS/NRAS/BRAF have a lower mutation rate in gastric cancer, furthermore, there is no consistent conclusion on the role of KRAS/NRAS/BRAF mutations in gastric cancer." (PMID 30416987, 2018). "Right-sided colon cancers are more likely to have genome-wide hypermethylation of the CIMP, hypermutated state via MSI-H, and BRAF mutations." (PMID 29652830, 2018). "A number of preclinical therapeutic strategies have been developed by combining EGFR pathway inhibitors with other target drugs in BRAF/KRAS mutant colon cancers." (PMID 30185207, 2018). "There was a significant difference in the expression of BRAF between the BRAF (V600E) MT and WT (p = 0.008) in colon cancers; and there was a significant difference in the expression of EGFR between the NRAS MT and WT (p = 0.021) in rectal cancers." (PMID 30416987, 2018). "It is remarkable that suppression of PTPN11 confers sensitivity to BRAF inhibitors (used in cancer therapeutics) in colon cancer by blocking signaling from the receptor tyrosine kinases to the RAS–MEK–ERK pathway." (PMID 29518019, 2018). "They showed that right-sided colon cancers had higher rates of MSI, more frequent aberrant activation of EGFR pathways, more frequent BRAF and PI3KCA mutations and an increased mutational burden compared to left-sided and rectal cancers." (PMID 29652830, 2018). "When analyzing the mutation rates of KRAS, NRAS, and BRAF in different locations, it can be found that KRAS gene mutation rate was significantly different in colon cancers (44.2%), rectal cancers (37.1%) and gastric cancers (0%) (p < 0.001)." (PMID 30416987, 2018). "Genetic markers were selected to represent the pathways most frequently altered in colon cancer, such as the WNT-pathway (surrogate marker osteopontin), mutations in the oncogenes KRAS and BRAF, and the DNA microsatellite status." (PMID 30340556, 2018). "CD133 mRNA expression, but not that of other cancer stem cell markers, predicted relapse-free survival in colon cancer patients; interestingly, CD133 expression was related to mutations in KRAS and BRAF." (PMID 29652830, 2018). "As expected, Right colon cancers fulfilled those features associated with sporadic MSI-CRC: Predominance of female cases and BRAF mutations, with an important amount of mucinous component, although, surprisingly, CIMP-High appeared more in rectal cases." (PMID 29632645, 2018). "In colon cancer, the low expression of LRP1 in tumor cells was strongly associated with right tumor location, poor differentiation, BRAF mutation, MSI-H and CIMP-H status in our cohort as well as in an independent CRC cohort." (PMID 29507659, 2018). "A recent study on Chinese patients showed that among KRAS, BRAF, PIK3CA and NRAS mutations in stage II to III colon cancers (n = 228), only PIK3CA mutations were an independent prognostic biomarker for poor OS among stage III patients." (PMID 29666387, 2018).
colon carcinoma (continued). "For example, in colon cancer HC4T, we found 12 of 79 variants were specific to FFEP DNA in addition to 67 common variants including three key mutations (in BRAF, MTOR and RUNX1)." (PMID 30680068, 2018). "It is known that various preclinical and therapeutic strategies using trametinib combined with another target drug in BRAF/KRAS mutant colon cancers were developed." (PMID 30185207, 2018). "Here we showed that K-ras and BRAF fold expression were decreased in colon cancer cells treated with extracted metabolites." (PMID 29564063, 2018). "There are known molecular differences between right- and left-sided colon cancer with the former more often being poorly differentiated, as well as more often KRAS and/or BRAF mutated." (PMID 29334918, 2018). "Complex 1 has an outstanding inhibitory effect against BRAF-mutant colon carcinoma and hepatocarcinoma cell growth; 1 and 2 are both more active than the free ligand and have the capacity to trigger early apoptotic processes." (PMID 28358339, 2017). "Given the high activity of VLX50 and VLX60 against the colon cancer cell line HCT116, which is KRAS mutated, the activity of these drugs was compared in three pairs of colon cancer cell lines with different KRAS and BRAF mutation status." (PMID 28415818, 2017). "The aim of this study was to investigate the influence of BRAF and KRAS mutation status on the association between aspirin use and overall survival after colon cancer diagnosis." (PMID 28125730, 2017). "Here, we wanted to identify RTKs that were potentially activated during treatment with the monoclonal antibody EGFR inhibitor cetuximab in previously identified intermediate cetuximab-sensitive KRAS and BRAF wild-type colon cancer cell lines." (PMID 28032592, 2017). "Right-sided colon cancers had higher rates of microsatellite instability, more frequent aberrant activation of the EGFR pathway including higher BRAF and PIK3CA mutation rates, and increased mutational burden compared to left-sided colon and rectal cancers." (PMID 29156800, 2017). "Next, we included colon cancer models able to associate the activity to the KRAS- and BRAF mutation status, established to have predictive and/or prognostic importance in this tumor type." (PMID 28415818, 2017). "The present study was designed to detect the potency of aspirin therapy in colon cancer cell lines according to major somatic driver mutations such as PIK3CA, BRAF, and KRAS mutations." (PMID 29152088, 2017). "The combination of the eiF4A inhibitor Episilvestrol and Bortezomib potentiates the killing of a wide variety of colon cancer cells with mutant KRAS/BRAF." (PMID 28030835, 2017). "A BRAF mutation was found in 17% (102/599) and a KRAS mutation was observed in 35% of colon tumors (212/599), in accordance with previous studies." (PMID 28125730, 2017). "We observed that Sorafenib inhibited AKT activity only in CaCO2 colon carcinoma cells that are BRAF and KRAS wildtype, and led to an increase in AKT activity in the other cell lines, which had mutations in either KRAS or BRAF." (PMID 26799289, 2016). "Tumor specific EGFR downstream signaling mutations in KRAS, BRAF, PTEN, and PIK3CA cause reduced benefit of cetuximab therapy in colon carcinoma patients." (PMID 27100871, 2016). "The difference in the sensitivity of mutant compared to wild-type BRAF colon cancer cells to AUY922-induced apoptosis was also reflected in clonogenic assays and in cells grown in 3-dimensional cultures." (PMID 27391062, 2016). "As anticipated, treatment with AUY922 resulted in marked reduction in activation of ERK and Akt in both wild-type (Lim1215 and Caco-2) and mutant (RKO and WiDr) BRAF colon cancer cells that was readily detectable at 16 hours." (PMID 27391062, 2016). "This suggests that mutant BRAF is less dependent on HSP90 for its stabilization than other HSP90 client proteins in colon cancer cells." (PMID 27391062, 2016).
colon carcinoma (continued). "The third is the alternative pathway, which starts from normal mucosa via villous, partly serrated adenomas (with KRAS, BRAF, and APC mutations and CIMP) and results in colon cancer with poor prognosis (with CIMP)." (PMID 26738600, 2016). "Here we report that colon cancer cells with mutant BRAF are also resistant to the heat shock protein 90 (HSP90) inhibitor AUY922, and that this is caused by rebound activation of ERK and Akt." (PMID 27391062, 2016). "On the other hand, introduction of active form of MEK1 or Akt rendered wild-type BRAF colon cancer cells resistant to AUY922." (PMID 27391062, 2016). "This reduction was sustained for at least 36 hours after treatment in wild-type BRAF colon cancer cells, but was diminished by 24 hours in mutant BRAF colon cancer cells." (PMID 27391062, 2016). "APC mutations were associated with poor prognosis in (5-fluorouracil treated) stage III colon cancers (p = 0.005; HR = 4.1), an effect that was further enhanced by mutations in MAPK pathway (KRAS, NRAS, BRAF) genes." (PMID 27729614, 2016). "Together, these results indicate that reactivation of ERK and Akt plays an important role in resistance of mutant BRAF colon cancer cells to AUY922." (PMID 27391062, 2016). "To examine the role of reactivation of ERK and Akt in resistance of mutant BRAF colon cancer cells to HSP90 inhibition, we treated RKO and WiDr cells with the MEK inhibitor AZD6244 or the PI3K inhibitor LY294002 before addition of AUY922." (PMID 27391062, 2016). "The levels of ERK and Akt activation in mutant BRAF colon cancer cells at 24 and 36 hours after treatment were comparable to the basal levels observed in the cells before treatment." (PMID 27391062, 2016). "In support, CDC37 was co-precipitated with Akt in mutant BRAF colon cancer cells in the presence of AUY922, whereas HSP90 was similarly co-precipitated with Akt in these cells when CDC37 was knocked down." (PMID 27391062, 2016). "Consistent with inhibition of reactivation of Akt and ERK, CDC37 knockdown sensitized mutant BRAF colon cancer cells to AUY922-induced apoptosis." (PMID 27391062, 2016). "Regardless, our results suggest that the combination of mutant BRAF inhibitors and HSP90 inhibitors is a useful strategy to improve their therapeutic efficacy in the treatment of mutant BRAF colon cancer." (PMID 27391062, 2016). "On the other hand, introduction of an active form of MEK1 (myr-MEK1) or an active form of Akt (myr-Akt) attenuated cell death induced by AUY922 in wild-type BRAF colon cancer cells." (PMID 27391062, 2016). "When AZD6244 and LY294002 were applied in combination, killing of mutant BRAF colon cancer cells by AUY922 was further enhanced." (PMID 27391062, 2016). "In the absence of a change in the expression levels of Akt, these results indicate that CDC37 plays an important role in phosphorylation of Akt in mutant BRAF colon cancer cells." (PMID 27391062, 2016). "The practical implications of the finding that rebound activation of ERK and Akt is responsible for resistance of mutant BRAF colon cancer cells to AUY922 was confirmed by using cells grown in 3-dimensional cultures." (PMID 27391062, 2016). "Strikingly, siRNA knockdown of CDC37 not only inhibited rebound activation of Akt in mutant BRAF colon cancer cells after treatment with AUY922, but also reduced the basal levels of activation of Akt in these cells." (PMID 27391062, 2016). "Our results suggest that CDC37 is a potential therapeutic target in the treatment of mutant BRAF colon cancers, in particular, in combination with HSP90 inhibitors." (PMID 27391062, 2016). "The second is the serrated pathway, which starts from normal mucosa via serrated adenomas (with BRAF mutations and CIMP) and results in colon cancer in the proximal colon with good prognosis (with MLH1 loss and MSI)." (PMID 26738600, 2016).